MIR10A (microRNA 10a)
Synonyms: hsa-mir-10a; MIRN10A; miRNA10A; mir-10a
Gene: MicroRNA gene on chromosome 17 (48,579,838 to 48,579,947, reverse strand). Ensembl gene ENSG00000284038.
Gene Ontology:
Biological process: miRNA-mediated post-transcriptional gene silencing
Cellular component: RISC complex
Homologues: Orthologues: chimpanzee ptr-mir-10a (100% identical), macaque mml-mir-10a (99% identical), rabbit MIR10A (99% identical), mouse Mir10a (98% identical), rat Mir10a (98% identical), guinea pig MIR10A (97% identical), dog MIR10A (94% identical), pig MIR10A (94% identical), zebrafish mir10a (75% identical), tropical clawed frog xtr-mir-10a (71% identical), zebrafish mir10c (68% identical), Drosophila melanogaster mir-10 (43% identical). Paralogues in human: MIR10B (65% identical), MIR100 (37% identical), MIR99A (36% identical), MIR125A (35% identical), MIR125B2 (33% identical), MIR125B1 (32% identical), MIR99B (32% identical).
Diseases named in the same sentence as MIR10A in open-access papers:
MIR10A is named in the same sentence as 9 diseases in open-access papers, as found by Europe PMC text mining. Sharing a sentence is not in itself a finding about the gene and the disease. The quoted sentences say what the papers report.
Sepsis (2 papers, 2021 to 2025). Sepsis is defined as life-threatening organ dysfunction caused by a dysregulated host response to infection. "Regarding MIR10A, it has been shown that miR-10a levels in PBMC at admission were significantly lower in sepsis patients compared with non-septic patients with infection, and with healthy controls." (PMID 33659006, 2021).
fatty liver (1 paper, 2023). "Based on our informatic analysis, we speculate that methylation changes in CpG sites involved in cell–cell signaling and MIR10A controlled TGF-β pathways act during childhood to result in early changes of fatty liver in adolescence, with implications for NAFLD onset and progression in adulthood." (PMID 36737504, 2023).
liver disease (1 paper, 2025). "Interestingly, many of the genes linked to the differentially methylated CpGs have been associated with liver disease progression (eg, DCP2, TRPV3, ARRB1, KCNIP4, MIR10A) and cancer formation or progression (eg, MTHFR, GRIK2, GSN, HOX3, KCNMA1)." (PMID 40275933, 2025).
steatosis (1 paper, 2023). Increased lipid within the cytoplasm of cells. "For MIR10A, 3 dmCpGs (cg01572694 (MIR10A CpG_10), MIR10A CpG_7, MIR10A CpG_9) were associated with steatosis score and one CpG (MIR10A CpG_7) associated with NAFLD after cell count adjustment." (PMID 36737504, 2023). "We identified dmCpGs in three genes (ANK1, MIR10A, PTPRN2) that were associated with steatosis score." (PMID 36737504, 2023).
infection (2 papers, 2016 to 2021). The state of being infected such as from the introduction of a foreign agent such as serum, vaccine, antigenic substance or organism. "At the second infection stage, we determined that MIR10a regulates HIV-1 proteins including Gag/Pol (p-value < 1☓10-16), which significantly interacts with small subunit (SSU) processome component, homolog (yeast) (KRR1) (p-value < 1☓10-16), also known as HIV-1 Rev binding protein 2 (HRB2)." (PMID 26897165, 2016).
MIR10A also shares sentences with these, for which no sentence is quoted: cancer (1 paper); liver fibrosis (1); lung carcinoma (1); neurological diseases (1).